OXGR1 (oxoglutarate receptor 1)
Description:
G protein-coupled receptor for dicarboxylates and amino dicarboxylates. Receptor for itaconate, a metabolite produced by myeloid lineages. In the respiratory epithelium, couples the binding of itaconate to the activation of GNA11 and downstream intracellular Ca(2+) release, leading to mucocilliary clearance of airborne pathogens. Receptor for leukotriene E4 (LTE4) produced by mast cells upon allergic inflammation. Binds with high affinity to LTE4 and elicits mucin release from pulmonary epithelium in response to airborne fungi allergens. Regulates mucin-producing goblet cell homeostasis (By similarity). Receptor for alpha-ketoglutarate produced by proximal tubule renal cells upon metabolic alkalosis. In an intrarenal paracrine signaling pathway, binds alpha-ketoglutarate and drives transepithelial salt reabsorption and bicarbonate secretion by SLC26A4/pendrin-positive intercalated cells (By similarity).
Synonyms: P2Y15; GPR80; GPR99; P2RY15; aKGR; CAON2
Tractability: Small molecule: it belongs to a druggable protein family. Antibody: UniProt places it where antibodies can reach, with high confidence; its Gene Ontology location is reachable by antibodies, with high confidence; UniProt predicts a signal peptide or a membrane-spanning region; the Human Protein Atlas places it where antibodies can reach. PROTAC: a small molecule that binds it is known.
Target class: Carboxylic acid receptor; Membrane receptor; Oxoglutarate receptor; Small molecule receptor (family A GPCR); Family A G protein-coupled receptor
Gene: Protein-coding gene on chromosome 13 (96,985,713 to 96,994,730, reverse strand). Ensembl gene ENSG00000165621.
Subcellular location: Cell membrane
Subcellular location (Human Protein Atlas): Plasma membrane
Pathways (Reactome):
Signal Transduction: Class A/1 (Rhodopsin-like receptors); G alpha (i) signalling events
Gene Ontology:
Molecular function: G protein-coupled receptor activity; protein binding; signaling receptor activity
Biological process: phospholipase C-activating G protein-coupled receptor signaling pathway; positive regulation of vascular associated smooth muscle contraction; G protein-coupled receptor signaling pathway
Cellular component: plasma membrane; membrane
Genetic constraint (gnomAD): Loss-of-function variants: 17 observed, 16.92 expected, observed/expected ratio (o/e) 1, 90% interval 0.69 to 1.5. The upper end of that interval is the gene's LOEUF score, 1.5, which puts it in group 6 of 6, group 1 being the genes least tolerant of losing a copy. Missense variants: 398 observed, 429.83 expected, observed/expected ratio (o/e) 0.93, 90% interval 0.85 to 1.01. Synonymous variants: 191 observed, 165.11 expected, observed/expected ratio (o/e) 1.16, 90% interval 1.03 to 1.3.
Homologues: Orthologues: macaque OXGR1 (98% identical), chimpanzee OXGR1 (95% identical), dog OXGR1 (90% identical), rabbit OXGR1 (89% identical), guinea pig OXGR1 (86% identical), rat Oxgr1 (86% identical), mouse Oxgr1 (85% identical), zebrafish oxgr1a.1 (42% identical), zebrafish oxgr1b (40% identical), zebrafish oxgr1a.2 (40% identical), zebrafish oxgr1a.3 (39% identical). Paralogues in human: P2RY1 (34% identical), SUCNR1 (31% identical), P2RY4 (30% identical), P2RY2 (30% identical), P2RY6 (29% identical), HCAR3 (21% identical), HCAR2 (20% identical), OXER1 (20% identical), GPR31 (20% identical), HCAR1 (20% identical), FFAR2 (20% identical), FFAR3 (20% identical), and 3 more.
Diseases named in the same sentence as OXGR1 in open-access papers:
OXGR1 is named in the same sentence as 26 diseases in open-access papers, as found by Europe PMC text mining. Sharing a sentence is not in itself a finding about the gene and the disease. The quoted sentences say what the papers report.
cardiac hypertrophy (4 papers, 2016 to 2022). "Loss of OXGR1 expression resulted in enhanced cardiac hypertrophy and marked reduction of contractile function following pressure overload stimulus." (PMID 27693579, 2016). "Here we demonstrated that OXGR1 expression during pressure-overload hypertrophy might be essential since in mice with complete loss of OXGR1 the extent of cardiac hypertrophy was augmented after 2 weeks of TAC." (PMID 27693579, 2016). "Previous studies have indicated that OXGR1 plays an important role in mucin regulation in otitis and cardiac hypertrophy." (PMID 32104923, 2020). "Others have recently reported that endogenous activation of the oxoglutarate receptor 1 (OXGR1) during pressure overload from TAC attenuated cardiac hypertrophy in the mouse by suppressing STAT3 activity." (PMID 30619368, 2018). "In conclusion, our data has identified OXGR1 as a novel modulator of pressure overload-induced cardiac hypertrophy." (PMID 27693579, 2016). "Using a mouse model with genetic ablation of the Oxgr1 gene, in this study we investigated the role of OXGR1 during pressure overload-induced cardiac hypertrophy." (PMID 27693579, 2016). "Here we used both in vivo and in vitro approaches to investigate the role of OXGR1 in cardiac hypertrophy." (PMID 27693579, 2016). "In this study we identify OXGR1 as a regulator of pathological cardiac hypertrophy." (PMID 27693579, 2016). "So OXGR1‐mediated protection is also possible due to the compensatory response to the other physiological changes induced by OXGR1KO, e.g., cardiac hypertrophy or impaired acid–base homeostasis." (PMID 32104923, 2020). "To investigate the effect of OXGR1 ablation under pathological conditions, we then performed transverse aortic constriction (TAC) to induce cardiac hypertrophy." (PMID 27693579, 2016).
Obesity (3 papers, 2020 to 2025). Accumulation of substantial excess body fat. "As an endogenous agonist of OXGR1, AKG has broad therapeutic potential such as extending lifespan, maintaining intestinal health, decreasing the risk of obesity, and facilitating macrophage activation via epigenetic alteration." (PMID 39872683, 2022). "To directly test if OXGR1 mediates the anti‐obesity effects of AKG, we used CRISPR gene‐editing technology to generate a global OXGR1KO mouse line." (PMID 32104923, 2020). "Our data suggest that exercise increases AKG and OXGR1 mediates anti‐obesity effects of AKG supplementation." (PMID 32104923, 2020). "Consistent with this point of view, we found enhanced anti‐obesity effects of AKG in the OXGR1 adrenal‐specific overexpression mouse model (GRP99OEAG)." (PMID 32104923, 2020). "Further, we used both loss‐of‐function and gain‐of‐function mouse models to determine whether AKG receptor OXGR1, expressed by the adrenal glands, is required for the anti‐obesity effects of AKG." (PMID 32104923, 2020). "We found that adrenal overexpression of OXGR1 enhanced the anti‐obesity effects of AKG." (PMID 32104923, 2020). "To assess if OXGR1AG is sufficient to mediate the anti‐obesity effects of AKG, we generated an OXGR1 adrenal‐selective reexpression (OXGR1REAG) mouse model by delivering HBAAV2/9‐OXGR1 virus into the adrenal gland of OXGR1KO mice." (PMID 32104923, 2020). "Alpha-KG not only increases the expression of thermogenic genes (i.e., Ucp1, Dio2, and Cidea) in the BAT, but also enhances lipolysis in the WATs through OXGR1-dependent adrenal activation, and as a result, administration of exogenous α-KG prevents HFD-induced obesity in mice." (PMID 40959283, 2025). "Interestingly, in our OXGR1REAG model, adrenal reexpression of OXGR1 cannot fully rescue the anti‐obesity effects of AKG, suggesting that other OXGR1 pathways may be involved." (PMID 32104923, 2020).
asthma (2 papers, 2016 to 2022). "In addition, the 2-oxoglutarate receptor 1 (OXGR1), a new cysteinyl receptor called receptor of the CysLTE or GPR99, is expressed in mast cells and its ligand LTE4 is able to recruit both eosinophils and basophils to the inflammatory site in asthma." (PMID 27092145, 2016).
male infertility (2 papers, 2022). The inability of the male to effect fertilization of an ovum after a specified period of unprotected intercourse. "Our study provides evidence that smooth muscle AKG/OXGR1 signaling may have a potential value in treating male infertility caused by related viral infection." (PMID 39872683, 2022). "In response to aging and heat stress, the expression of OXGR1 was significantly decreased, suggesting that it may play an important role in the epididymal smooth muscle, and its decreasing may be associated with male infertility." (PMID 39872688, 2022). "Therefore, delineating the role of AKG/OXGR1 system in male infertility will provide direct targets for clinical application to improve male reproduction by nutrients." (PMID 39872683, 2022). "NBCe1-defective mice causes 100% mortality before day 25, which suggests that smooth muscle AKG/OXGR1-NBCe1 pathway may play a momentous role in the therapy of male infertility." (PMID 39872683, 2022).
diabetes (1 paper, 2024). "The activation of α-ketoglutarate receptor OXGR1 and succinate receptor GPR91 may be relevant in metabolic stress-related diseases such as diabetes." (PMID 39506854, 2024).
heart failure (1 paper, 2016). Inability of the heart to pump blood at an adequate rate to meet tissue metabolic requirements. "One member of this family, the oxoglutarate receptor 1 (OXGR1), may have a crucial role in the heart because it acts as a receptor for α-ketoglutarate, a metabolite that is elevated in heart failure patients." (PMID 27693579, 2016).
hypertrophic cardiomyopathy (1 paper, 2022). A condition in which the myocardium is hypertrophied without an obvious cause. "OXGR1 is expressed in Glp‐1‐positive enteroendocrine cells and has been variously been implicated in respiratory epithelial mucin production, hypertrophic cardiomyopathy, fibroblast proliferation, and axon growth but not guidance." (PMID 35851763, 2022).
ischemic stroke (1 paper, 2022). A stroke disorder caused by obstruction of blood flow to the brain, due to thrombotic (local blood clot formation) or embolic (due to a blood clot or other material traveling from another site) event. "An OXGR1 variant of unknown significance has also been linked to early ischemic stroke in families with a history of stroke." (PMID 35851763, 2022).
nasal polyps (1 paper, 2022). "OXGR1 may play a role in vascular responses in vascular SMCs distributed in the human nasal mucosa and may be involved in chronic signs and symptoms such as nasal polyps in patients with aspirin-exacerbated respiratory disease." (PMID 39872683, 2022).
rectal adenoma (1 paper, 2012). "Array CGH found that copy number increase of GPNMB (7p15.2), OXGR1 (13q32.1), C13orf27 (13q32.2-q34), PMEPA1 (20q13.31), PHACTR3 (20q13.32) and decrease of SMAD4 (18q21.2), BCL2 (18q21.33) occurred in both rectal adenoma and carcinoma." (PMID 23158542, 2012).
sperm (1 paper, 2022). "In this study, we found that aging and heat stress significantly reduced the expression of epididymal OXGR1 and impaired sperm maturation, whereas drinking water supplemented with 2% AKG effectively reversed sperm maturation disorder caused by aging and heat stress." (PMID 39872683, 2022).
viral infection (1 paper, 2022). "Taken together, viral infection has a significant impact on male reproduction, which further highlights the potential role of AKG/OXGR1 system in the treatment of male reproductive decline caused by associated viral infection." (PMID 39872683, 2022).
bacterial infection (2 papers, 2023 to 2025). "Taken together, these results suggest that ITA, but not LTE4 or α-KG, is the natural ligand of Oxgr1 in respiratory epithelium during bacterial infection." (PMID 36919698, 2023).
tumor (2 papers, 2007 to 2025). "For example, itaconate promotes tumor cell proliferation and migration via OXGR1 activation in the tumor microenvironment, similar to its effects in other physiological and pathological contexts." (PMID 40729001, 2025).
cardiovascular disease (1 paper, 2022). "Moreover, this study explained the theory of exercise-induced muscle fiber vascularization, provided a dietary strategy basis for AKG addition in animal feed and safety in humans, and created a new treatment for AKG/OXGR1 signaling pathway in skeletal muscle aging and cardiovascular disease." (PMID 39872069, 2022).
infection (1 paper, 2023). The state of being infected such as from the introduction of a foreign agent such as serum, vaccine, antigenic substance or organism. "Notably, the phenotype of defective airway pathogen clearance was recapitulated in the same infection model in Oxgr1–/– mice." (PMID 36919698, 2023). "Fourth, we provide genetic evidence in mouse infection models to support the functional interaction between IRG1/ITA and OXGR1." (PMID 36919698, 2023).
OXGR1 also shares sentences with these, for which no sentence is quoted: cancer (2 papers); Hypertension (2); Azoospermia (1); kidney disease (1); lung carcinoma (1); nicotine dependence (1); otitis (1); renovascular hypertension (1); respiratory disease (1); Stroke (1).